FEN1 (flap structure-specific endonuclease 1)
Diseases named in the same sentence as FEN1 in open-access papers (continued):
Sharing a sentence is not in itself a finding about the gene and the disease.
breast carcinoma (continued). "This study examined the effects of the FEN1 inhibitor FEN1-IN-4 on breast cancer cell lines including four TNBC cell lines and whether it is a useful therapeutic agent in breast cancer therapy in monotherapy or in combination with IR." (PMID 38396787, 2024). "Since this study revealed that, notably, three out of four TNBC and other breast cancer cell lines show a good response to FEN1-IN-4 monotherapy and combination therapy with IR, FEN1-IN-4 may expand the therapeutic spectrum as a potential target therapy." (PMID 38396787, 2024). "In addition, the healthy fibroblasts had lower levels of FEN1 foci than the breast cancer cells, which had much higher FEN1 foci count and FEN1 intensity levels." (PMID 38396787, 2024). "In vivo, high FEN1 mRNA expression worsens the prognosis of breast cancer patients." (PMID 38396787, 2024). "Due to the increased expression in breast cancer tissue, FEN1 could represent a new tumor and prognosis marker and FEN1-IN-4 may serve as a new potent agent in personalized medicine and targeted breast cancer therapy." (PMID 38396787, 2024). "We have studied the role of FEN1 in drug resistance of breast cancer cells." (PMID 37326412, 2023). "Importantly, FEN1 expression seems to be a predictive marker for resistance to tamoxifen in ERα-positive breast cancers." (PMID 37762489, 2023). "Additionally, down-regulating FEN1 of breast cancer cells by letrozole enhanced the cisplatin sensitivity via ERK/Elk-1 signaling." (PMID 35173534, 2022). "Furthermore, miR-140 acts as a tumor suppressor in breast cancer by inhibiting FEN1 from repressing DNA damage repair." (PMID 36324569, 2022). "Our previous study demonstrated that overexpression of microRNA-140 (miR-140) could enhance the drug sensitivity of breast cancer cells and reduce the drug resistance of adriamycin-resistant breast cancer cells by targeting FEN1." (PMID 35883563, 2022). "FENi #2 was used to treat breast cancer by targeting FEN1 and disrupting chromatin stability." (PMID 35883563, 2022). "Ectopic expression of FEN1 in breast cancer enhances adriamycin resistance." (PMID 35883563, 2022). "By analyzing clinical data, it was found that FEN1 protein expression is related to the aggressiveness of epithelial ovarian and breast cancer and the prognosis of patients, and high expression of FEN1 is positively correlated with the survival rate of patients." (PMID 35883563, 2022). "The sensitivity of tamoxifen-resistant cell lines to the FEN1 blockade was also increased and may be used to treat advanced breast cancer in the future, providing a new targeted therapy for tamoxifen-resistant cases." (PMID 35883563, 2022). "Another mechanism for enhanced breast cancer cells death may be enhanced intracellular ROS generation due to treatment with ATO combined with inhibition of Flap Endonuclease 1 (FEN1) expression." (PMID 36619302, 2022). "Among all types, the greatest expression of FEN1-mRNA has been found in breast cancer samples." (PMID 34809722, 2021). "Furthermore, SC13, a FEN1 inhibitor, showed cytotoxic and inhibitory activity in human breast cancer in a mouse model." (PMID 34277392, 2021). "In addition, a high level of FEN1 mRNA was predictive of short breast cancer-specific survival (BCSS) (p < 0.001, HR = 2.170, 95% CI = 1.355–2.031)." (PMID 34117958, 2021). "Similarly, IHC analysis of FEN1 protein expression in breast cancer samples revealed high expression in these samples, and a positive correlation between expression and increased relative cancer risk was found." (PMID 34809722, 2021). "The same decrease in both proteins was observed in cigarette smoke-induced breast cancer cells treated with resveratrol alone, where it was also detailed that p21 levels increased and affected the binding of FEN1 to PCNA, thus inhibiting the long patch base excision repair pathway." (PMID 33330091, 2020). "Hence, YY1-dependent repression of FEN1 leads to sensitization of breast cancer cells to DNA-damaging agents." (PMID 31824839, 2019).
breast carcinoma (continued). "High level of FEN1 expression in breast cancer cells could reflect the enhanced proliferation or increased DNA damage of cancer cells." (PMID 31777591, 2019). "Furthermore, FEN1 was found be regulated by the transcriptional repressor Ying Yang 1 (YY1) in response to DNA damaging agents in the context of breast cancer." (PMID 31534853, 2019). "A combination of curcumin with cisplatin could enhance breast cancer cell sensitivity to cisplatin through down-regulation of FEN1 expression." (PMID 29541412, 2018). "This suggests that FEN1 overexpression may promote cisplatin resistance, and that FEN1 could be a potential therapeutic target for the treatment of cisplatin resistance in breast cancer." (PMID 29541412, 2018). "FEN1 could be a potential therapeutic target for the treatment of cisplatin resistance in breast cancer." (PMID 29541412, 2018). "Flap endonuclease 1 (FEN1) overexpression promotes breast cancer." (PMID 29541412, 2018). "In accordance with our previous data, these results suggested that curcumin could inhibit breast cancer cell proliferation, including cisplatin-resistant cells through FEN1 down-regulation." (PMID 29541412, 2018). "An RNAi-mediated down-regulation of FEN1 expression could enhance breast cancer cell sensitivity to cisplatin." (PMID 29541412, 2018). "This suggests that ERK phosphorylation may contribute to cisplatin-induced FEN1 overexpression in breast cancer cells." (PMID 29541412, 2018). "FEN1 overexpression is correlated to cancer, and FEN1 is highly expressed in the cells of metastatic prostate cancer, gastric cancer, neuroblastomas, pancreatic cancer, lung cancer, and breast cancer." (PMID 29541412, 2018). "This suggests that FEN1 overexpression promotes cisplatin resistance in breast cancer cells." (PMID 29541412, 2018). "The possible mechanism of how curcumin could down-regulate FEN1 expression and increase the sensitivity of breast cancer cells to cisplatin was explored in this study." (PMID 29541412, 2018). "Curcumin may inhibit breast cancer cell proliferation through the transcription factor Nuclear factor (erythroid-derived 2)-like 2 (Nrf2) mediated down-regulation of Fen1 expression." (PMID 28724427, 2017). "However, during neoplastic transformation, this regulation mechanism is abolished, leading to FEN1 overexpression in breast cancer cells." (PMID 25885449, 2015). "The Northern dot blotting results showed that FEN1 expression levels in breast cancer cell lines, MDA-MB-4355 and MDA-MB-231, increased significantly (by more than 8 folds) after the treatment with DNA-damaging agents, such as camptothecin, cytochalasin D, MMC, and gamma irradiation." (PMID 25885449, 2015). "Furthermore, we observe that the level of FEN1 is inversely correlated with cancer drug and radiation resistance and with survivorship in breast cancer patients." (PMID 25885449, 2015). "In this study, we have presented data to support such a notion that FEN1 over-expression has an inverse correlation with survivorship of breast cancer patients and may serve as a prognostic biomarker." (PMID 25885449, 2015). "Furthermore, L1CAM, CDKN1C, and FEN1, which have been reported to be relevant to breast cancer – the most sensitive subtype to docetaxel among the nine NCI-60 cancer subtypes – were clustered just next to the drug vector." (PMID 18237428, 2008). "This study investigated the effects of FEN1 inhibitor FEN1-IN-4 in combination with ionizing radiation on cell death, clonogenic survival, the cell cycle, senescence, doubling time, DNA double-strand breaks and micronuclei in breast cancer cells, breast cells and healthy skin fibroblasts." (PMID 38396787, 2024). "The results showed that curcumin downregulated the expression of FEN1 in a dose-dependent manner both in vitro and in vivo, suggesting that FEN1 could be a potential therapeutic target to alleviate cisplatin resistance in breast cancer." (PMID 37628772, 2023).
breast carcinoma (continued). "We hypothesised a role for FEN1 in breast cancer pathogenesis." (PMID 34117958, 2021). "In addition, high expression of FEN1 was also found in breast cancer and gastric cancer." (PMID 33224879, 2020). "In both breast cancer and lung cancer drug-resistant cells, the level of FEN1 medicated DNA damage repair was significantly increased and the inhibition of FEN1 expression could promoted the drug-resistant cells sensitivity to Tamoxifen and Cisplatin respectively." (PMID 32586310, 2020). "We then investigated whether YY1 bound to the FEN1 promoter region in MCF7 breast cancer cells by conducting a chromatin immune-precipitation-PCR (ChIP-PCR) and showed that the FEN1 promoter was specifically pulled-down by an YY1-specific antibody but not the control antibody." (PMID 25885449, 2015). "Furthermore, to gain insights into the impact of FEN1 levels on the response of human cancer to therapeutic treatments, we determine FEN1 levels in human breast cancer specimens and correlate them to the response to treatments and the survivorship of corresponding breast cancer patients." (PMID 25885449, 2015). "In breast cancer, elevated YY1 levels have been found to lead to FEN1 downregulation, increasing cancer cell sensitivity to mitomycin C or Taxol." (PMID 40867231, 2025). "Combining small molecule FEN1 inhibitors (NSC-281680 and SC13) and chemotherapeutics (TMZ, cisplatin, or 5-FU) sensitized colon and breast cancer cells." (PMID 37762489, 2023). "Based on the data gathered, we propose, for the first time, that SOC therapies used in ER+ breast cancer reduce the expressions of DNA repair proteins, XRCC1, FEN1, BRCA1, BRCA2 and RAD51, caretakers in maintaining genomic integrity." (PMID 37914699, 2023). "FEN1-mediated DNMT3a up-regulation, released the suppression of its targeting MET and EGFR, and promoted breast cancer cell proliferation by activating PI3K/AKT and MAPK/ERK pathways in MCF-7cells." (PMID 35620052, 2022). "Therefore, FEN1 may serve as a key biomarker for ovarian and breast cancer." (PMID 35883563, 2022). "ERCC5, pertaining to the FEN1/XPG endonuclease family, is ectopically expressed in gastric cancer, breast cancer, scaly cell carcinoma and liver cancer." (PMID 35934844, 2022). "Flap structure-specific endonuclease 1 (FEN1) is a key enzyme in base excision repair (BER) and DNA replication, and it is related to the chemoresistance of multiple cancers such as breast cancer, non-small cell lung cancer (NSCLC), and osteosarcoma." (PMID 33546351, 2021). "By reproducing this result in other breast cancer cell lines; MDA-MB-231, T47D, and HCC1937 as well as lung and colorectal cancer cell lines, it has been concluded that FEN1 promotes cancer cell growth." (PMID 34809722, 2021). "Whereas the FEN1 inhibitor, SC13 with an IC50 of 4.2 μM, supressed growth of breast cancer cell lines and also sensitised cells to cisplatin, 5-FU and TMZ." (PMID 32648895, 2020). "This suggests that curcumin can down-regulate FEN1 expression by reducing ERK phosphorylation levels, and then increase breast cancer cell sensitivity to cisplatin." (PMID 29541412, 2018). "We observe that FEN1 is significantly up-regulated upon treatment of chemotherapeutic drugs such as mitomycin C (MMC) and Taxol in breast cancer cells." (PMID 25885449, 2015). "In that cohort, patients with FEN1-high and YY1-low expression had both statistically significantly poor overall and disease-free postoperative survivals, a fact suggesting that FEN1 and YY1 might have inverse impact on the survival of breast cancer patients." (PMID 25885449, 2015). "In the most aggressive breast cancer subtype, triple-negative breast cancer (TNBC), PLK4 has been reported to promote migration and invasion of cancer cells via its modulation by FEN1 (Flap endonuclease-1 (FEN1), a nuclease important for DNA replication and repair processes." (PMID 41092110, 2025).
breast carcinoma (continued). "Studies demonstrate that YY1 functions as a transcriptional repressor of FEN1, and YY1 dissociates from the FEN1 promoter to increase its expression under DNA-damaging agent (mitomycin and taxol) treatment, consequently promoting resistance to drugs in breast cancer cells." (PMID 40867514, 2025). "FEN1 was reported to elevate the expression of DNMT3A and promote their interaction among FEN1/PCNA/DNMT3A and suppressed the expression of miR-200a-5p, leading to upregulation of miR-200a-5p targets, MET and EGFR, which contribute to enhancement of growth of breast cancer cells." (PMID 35620052, 2022). "AEs enhanced breast cancer sensitivity to PTX by decreasing cell proliferation both through the ROS/Nrf2 pathway and via the downregulation of p-ERK, and these mechanisms resulted in the decrease in FEN1 expression leading to DNA damage accumulation and DNA replication reduction." (PMID 31998443, 2020). "Although these FEN1 polymorphisms are not genetically associated with FECD, researchers have associated c.4150G>T (rs4246215) with deregulated FEN1 transcript expression in lung- and breast cancer tissues." (PMID 30260965, 2018).
lung carcinoma (29 papers, 2015 to 2025). "Prior studies showed mutation in FEN1 l inking lung cancer progression in an age-dependent manner in mice exposed to benzo[α]pyrene which is present in tobacco smoke 21,57." (PMID 32702724, 2020). "Prior studies showed mutation in FEN1 linking lung cancer progression in an age-dependent manner in mice exposed to benzo[α]pyrene which is present in tobacco smoke." (PMID 33013423, 2020). "Taken together, our findings implicated FEN1 in DNA replication and repair as a mechanism of lung cancer development and cancer drug resistance." (PMID 28371273, 2017). "This suggested that the evolution of the structure and function of FEN1 in lung cancer and prostate cancer may be the primary topics associated with FEN1 research." (PMID 33827468, 2021). "In addition, the FEN1 was up-regulated in lung cancer cells and associated with the clinical lung cancer stage." (PMID 31534853, 2019). "Deregulated FEN1 expression was associated with rs4246215 in lung cancer tissues." (PMID 30260965, 2018). "Moreover, FEN1 mutations that abrogate nuclease activity have been detected in lung cancers and corresponding knock-in mice are viable with autoimmune, chronic inflammatory, and cancer phenotypes." (PMID 29928064, 2018). "Next, we investigated whether the FEN1 expression level was associated with the malignancy of lung cancers." (PMID 28371273, 2017). "Also, FEN-1 mutant mouse showed a high risk of developing lung cancer upon exposure to B[α]P-containing agents such as tobacco smoke." (PMID 26431531, 2015). "Regarding FEN1 regulation, PRMT1-mediated methylation stabilizes FEN1 protein levels, improving DNA repair capacity and therapy resistance in lung cancer cells." (PMID 41204384, 2025). "Fen1 is an essential tumor suppressor protein reported to be overexpressed in brain, testicular, and lung cancers." (PMID 40685548, 2025). "PRMT1 was one of the arginine methyltransferases, which epigenetically up-regulated FEN1 leading to cisplatin and paclitaxel resistance by elevating the DNA repair ability and inhibiting the apoptosis of lung cancer cells." (PMID 40701777, 2025). "In lung cancer, FEN1 overexpression enhanced tumor progression, whereas after down-regulation or FEN1 inhibition, cells became more sensitive to cisplatin treatment." (PMID 38396787, 2024). "They showed that FEN1 is critical for the rapid proliferation of lung cancer cells, as when FEN1 is suppressed, a decrease in DNA replication and the accumulation of DNA damage were observed, leading to apoptosis." (PMID 39796653, 2024). "In non‐small cell lung cancer, cell cycle arrest at the G1/S or G2/M phase was induced after FEN1 knockdown." (PMID 37326412, 2023). "FEN1 depletion has been proven to be sensitive to cisplatin treatment in lung cancer, suggesting that this novel type of anticancer agent is an effective strategy against FEN1-overexpressing cancers." (PMID 35414100, 2022). "FEN1 expression is increased in metastatic prostate cancer cells, gastric cancer cells, pancreatic cancer cells, and lung cancer cell lines, and with tumor progression." (PMID 35884586, 2022). "Studies have shown that the high expression of the FEN1 gene is essential for the rapid proliferation of lung cancer cells, and the FEN1 gene can also increase the resistance of lung cancer cells to cisplatin." (PMID 36506331, 2022). "FEN1 mRNA overexpression has also been demonstrated in lung cancer cell lines and gastric cancer cell lines." (PMID 33919707, 2021). "Adverse prognostic and/or predictive significance of FEN1 has been shown in lung cancer and hepatocellular carcinomas." (PMID 33919707, 2021). "By using the A549 cell line as a research model, we demonstrated that FEN1 was essential for proliferation and cisplatin resistance of lung cancer cells." (PMID 28371273, 2017).